COL4A1 (collagen type IV alpha 1 chain)
Diseases named in the same sentence as COL4A1 in open-access papers (continued):
Sharing a sentence is not in itself a finding about the gene and the disease.
metastatic colorectal cancer (1 paper, 2024). "Previously, an increase in COL4A1 expression was noted in regions on 10 × Visium slides where metastatic colorectal cancer was colocalized with fibroblasts." (PMID 39639369, 2024).
Microcornea (1 paper, 2025). A congenital abnormality of the cornea in which the cornea and the anterior segment of the eye are smaller than normal. "The COL4A1 variant c.2317G>A (p.Gly773Arg), previously reported in patients with bilateral CC and neurological features, was found in patient 30, who primarily showed a purely ocular phenotype with bilateral CC and microcornea." (PMID 41155148, 2025).
myocardial ischemia (1 paper, 2018). A disorder of cardiac function caused by insufficient blood flow to the muscle tissue of the heart. "Disease Biomarker Pathway analysis identified Myocardial Ischemia as the third most enriched pathway (FDR-adjusted p = 1.3e−2), featuring 11 SNP loci on our list out of 886 pathway objects, including annexin V, ANRIL, COL4A1, dynein, HXK4, nectin-2, PPAR-gamma, prolidase, Tcf(Lef), UGT, and VEGFR-2." (PMID 29765130, 2018).
nephrogenic diabetes insipidus (1 paper, 2016). Nephrogenic diabetes insipidus (NDI) is characterized by polyuria with polydipsia, recurrent bouts of fever, constipation, and acute hypernatremic dehydration after birth that may cause neurological sequelae. "In accordance with nephrogenic diabetes insipidus, untreated 4-month-old Col4a1 mutant mice did not have elevated levels of the water channel aquaporin 2 (Aqp2) that plays a crucial role in tubular water reabsorption and urine concentration." (PMID 26839400, 2016).
nonalcoholic steatohepatitis (1 paper, 2022). "ADMSCs ameliorate the development of fibrosis during the progression of nonalcoholic steatohepatitis Col4a1 and Col1a1 were significantly downregulated." (PMID 34985174, 2022).
orchitis (1 paper, 2021). Inflammation of one or both testes due to viral or bacterial infections. "In all the collagen members detected to be expressed in Lc, the expression profile shifted greatly during EAO, and Col3a1, Col4a1, and Col1a2 became the main collagens expressed during orchitis." (PMID 35111154, 2021).
osteoarthritis (1 paper, 2021). A noninflammatory degenerative joint disease occurring chiefly in older persons, characterized by degeneration of the articular cartilage, hypertrophy of bone at the margins and changes in the synovial membrane. "For instance, Col1a1 and Col4a1 are collagen fibers that were associated with the progression of osteoarthritis." (PMID 33407721, 2021).
osteomyelitis (1 paper, 2022). An acute or chronic inflammation of the bone and its structures due to infection with pyogenic bacteria. "The results suggested that both COL4A1 and COL18A1 were highly expressed in subgroup A osteomyelitis." (PMID 36544487, 2022). "Between the two gene subtypes, the expression of 3 collagen-related genes was significantly different, among which COL4A1, COL8A2 and COL18A1 were all highly expressed in gene cluster A osteomyelitis." (PMID 36544487, 2022).
pancreatic ductal adenocarcinoma (1 paper, 2022). An infiltrating adenocarcinoma that arises from the epithelial cells of the pancreas. "The predominant expression of COL4A1 in CAFs has been previously reported in pancreatic ductal adenocarcinoma." (PMID 35455650, 2022).
peroxisomal disease (1 paper, 2025). A group of congenital disorders of lipid metabolism, caused by loss of the normal peroxisomes. "However, molecular analysis for one patient identified a pathogenic variant in PEX6, which is associated with peroxisomal diseases, specifically Zellweger spectrum disorder, and another was found to carry a COL4A1 variant associated with Stickler syndrome." (PMID 40114034, 2025).
pituitary adenomas (1 paper, 2023). "Contrary to the results of proteomic quantification, COL4A1 was downregulated in invasive pituitary adenomas (P<0.05)." (PMID 36936141, 2023). "COL4A1 was not significantly correlated with the invasiveness of pituitary adenoma (P>0.05)." (PMID 36936141, 2023).
Polydipsia (1 paper, 2016). Excessive thirst manifested by excessive fluid intake. "Polyuria (∼4.7-fold increase) and polydipsia (∼1.6-fold increase) were also observed in 2.5-month-old Col4a1+/Svc mice." (PMID 26839400, 2016).
posterior polymorphous corneal dystrophy (1 paper, 2020). Posterior polymorphous corneal dystrophy (PPCD) is a rare mild subtype of posterior corneal dystrophy characterized by small aggregates of apparent vesicles bordered by a gray haze at the level of Descemet membrane, generally with no effect on vision. "For example, mutations in the COL4A1 and COL8A2 genes have been shown to induce PA, posterior polymorphous corneal dystrophy (PPCD), or corneal endothelial dystrophy." (PMID 33304895, 2020).
postmenopausal osteoporosis (1 paper, 2020). Metabolic disorder associated with fractures of the femoral neck, vertebrae, and distal forearm. "It is worth mentioning that regulation of the TGF‐β/Smad2/COL4A1 signaling pathway promotes osteogenic differentiation of bone marrow stromal cells and is of great significance for the new treatments strategy for postmenopausal osteoporosis." (PMID 32496000, 2020).
Salmonella Infections (1 paper, 2013). Infections with bacteria of the genus SALMONELLA. "Accordingly, our RT-qPCR data showed decreased COL4A1 as well as VCL expression upon Salmonella infection." (PMID 23826261, 2013).
scleroderma (1 paper, 2023). Scleroderma is a rare autoimmune connective tissue disorder characterized by abnormal hardening of the skin and, sometimes, other organs. "Genes associated with ECM components, such as COL4A1, heparan sulfate proteoglycan 2 (HSPG2), and actin beta (ACTB), as well as phospholipase C gamma 2 (PLCG2), fatty binding protein 4 (FABP4), and galectin 1 (LGALS1), also showed higher expression levels in scleroderma." (PMID 37443817, 2023).
Skeletal myopathy (1 paper, 2018). "Importantly, postnatal treatment with 4PBA also reduced ICH and skeletal myopathy severities in Col4a1 mutant mice, which has significant clinical implications for patients with COL4A1 and COL4A2 mutations." (PMID 29895609, 2018). "ICH severity in untreated Col4a1+/Δex41 mice was similar to that observed in untreated Col4a1+/Δex41 mice at 2MO (exercised) and 8MO (unexercised), and both ICH and skeletal myopathy were significantly suppressed in Col4a1+/Δex41 mice provided with 4PBA from E9.5 to 3MO." (PMID 29895609, 2018). "Together, these findings underscore the importance of early intervention and suggest that postnatal treatment can be effective in reducing COL4A1-related ICH and skeletal myopathy when it is not discontinued." (PMID 29895609, 2018).
systemic sclerosis (1 paper, 2022). A chronic disorder, possibly autoimmune, marked by excessive production of collagen which results in hardening and thickening of body tissues. "Mouse models relevant to systemic sclerosis, have confirmed increased gene expression of COL4A1 in the skin and lung." (PMID 36404995, 2022).
teratocarcinoma (1 paper, 2021). A germ cell tumor characterized by the presence of an embryonal carcinoma component and a teratoma component. "Study performed 40 years ago revealed that treatment of F9 teratocarcinoma cells with DNA demethylating agent 5-Azacytidine results in increase Col4a1 expression, suggesting for the first time that DNA methylation may play important role in its expression." (PMID 33777319, 2021).
tongue cancer (1 paper, 2020). A malignant neoplasm affecting the tongue. "Sequencing and qPCR results demonstrated that COL4A1 and COL4A6 were significantly upregulated in tongue cancer, suggesting that these genes may play important roles in the occurrence and development of tongue cancer." (PMID 32236620, 2020).
tuberous sclerosis (1 paper, 2026). Hereditary disease characterized by seizures, intellectual disability, developmental delay, and skin and ocular lesions. "Two patients had tuberous sclerosis caused by pathogenic variants in the TSC2 gene, and one patient carried a COL4A1 variant predisposing to perinatal hemorrhagic stroke." (PMID 41563000, 2026).
urothelial carcinoma (1 paper, 2019). A malignant neoplasm derived from the transitional epithelium of the urinary tract (urinary bladder, ureter, urethra, or renal pelvis). "Studies of the Miyake laboratory demonstrated that the expression of COL13A1 and COL4A1 by cancer cells of human urothelial carcinoma plays a crucial role in tumor invasion through the induction of tumor budding." (PMID 31581653, 2019).
Vestibular schwannoma (1 paper, 2021). A vestibular schwannoma (also known as acoustic neuroma, acoustic neurinoma, or acoustic neurilemoma) is a benign, usually slow-growing tumor that develops from the VIIIth cranial nerve supplying the inner ear. "Low expression of COL4A1 and COL5A1 was associated with recurrence of vestibular schwannoma, while high expression of NPY was associated with recurrence of vestibular schwannoma." (PMID 34691289, 2021).
tumor (125 papers, 2006 to 2026). "The search for the upregulated genes in three types of CSCs revealed Actn3, Ccnd2, Col4a1, and Col4a2, which have been linked to tumor aggressiveness, poor prognosis, cancer cell proliferation, and cell migration." (PMID 35063003, 2022). "In this context, COL4A1 is potentially associated with CAF by modulating the immunosuppressive TME toward pro-tumor effects, resulting in worse prognostic outcomes." (PMID 35455650, 2022). "Six diagnostic genes were mutated in descending frequency in the tumor group: COL4A1, ABCA8, MAMDC2, FAP, TMEM100, and LY6E." (PMID 36685898, 2022). "Col IV activates intracellular signaling events to promote cell survival, proliferation, and tumorigenesis, and the aberrant expression of COL4A1 is associated with tumor progression." (PMID 35455650, 2022). "For example, COL4A1, which encodes a major component of type IV collagen, acts as an oncogene to facilitate tumour cell metastasis via activation of the FAK-Src signalling pathway." (PMID 34930901, 2021). "The expression of Col4a1 is relatively higher in C13:Bsl-G cells, differentiating them from C12:Bsl associated tumor cells." (PMID 32840210, 2020). "Many over-expressed genes in tumor-associated T cells were involved in tissue remodeling (e.g., Col1a1, Col4a1, Fn1, Lamc1, Mmp2, Mmp10, Timp3) and cell motility/adhesion (Rhoc, Itga1, Itgav)." (PMID 31477729, 2019). "High COL4A1 was revealed to be associated with advanced tumor stage as well as with bad overall and disease-free survival in HCC patients." (PMID 29921304, 2018). "Furthermore, studies on COL4A1 have revealed that COL4A1 produced by BC cells promotes tumor budding and is associated with poor prognosis." (PMID 40427030, 2025). "Moreover, COL4A1 expression showed a strong positive relationship with marker genes for pro-tumoral immune cell infiltration, such as Tregs, M2 macrophages, and tumor-associated macrophages (TAMs) and immunosuppressive cytokine expression." (PMID 40351420, 2025). "Moreover, overexpression of COL4A1 has been linked to angiogenesis, facilitating the formation of new blood vessels that support rapid tumor growth and dissemination." (PMID 39850811, 2024). "Overall, the results of our study suggest that COL4A1 overexpression in stromal cells may function as a potential regulator of the tumor-supporting TME composition associated with the poor prognosis of patients with LGG, PAAD, SKCM, and STAD." (PMID 35455650, 2022). "Collectively, our data showed that high expression levels of COL4A1 are associated with pro-tumor effects via upregulation of the expression levels of immunosuppressive cytokines, thereby potentially affecting the poor prognosis of patients with LGG, PAAD, SKCM, and STAD." (PMID 35455650, 2022). "Collectively, our data suggest that COL4A1 overexpression in stromal cells may be a potential regulator of tumor-supporting TME composition associated with poor prognosis." (PMID 35455650, 2022). "COL4A1, a component of the basement membrane, was shown to be progressively upregulated across tumor stages, suggesting its involvement in disease advancement." (PMID 41291892, 2025). "As the tumor progressed, COL4A1, COL4A2 and COL4A6 expression gradually increased, and COL4A3, COL4A4 and COL4A5 gradually decreased." (PMID 40351420, 2025). "Knockdown and functional analysis of COL3A1 and COL4A1 in ESCA cells were performed to assess their tumor-promoting roles." (PMID 40087784, 2025). "EC5 displayed high expression levels of genes related to ECM remodeling (COL4A1,COL4A2,HSPG2,MMP2,SPARC),which have been previously implicated in tumor angiogenesis." (PMID 41394809, 2025). "The study revealed that COL4A1/2 plays a critical role in stromal cell differentiation and is significantly enriched at the tumor–stroma interface, where it promotes invasive tumor growth through interactions with ITGA1/B1." (PMID 40867511, 2025).
tumor (continued). "Functional assays demonstrated that knocking down COL3A1 and COL4A1 led to decreased cell proliferation, colony formation, and migration, indicating their critical roles in tumor progression." (PMID 40087784, 2025). "The expression of COL4A1 was significantly positively correlated with the markers of tumor immune cell infiltration (such as Treg, M2 and TAM) and immunosuppressive cytokines." (PMID 38907304, 2024). "Of the 24 tissue sections, proteins encoded by COL4A1, IGFBP3, and TIMP1 were slightly up-regulated in tumor tissues, while GHRL and GJA1 proteins were relatively down-regulated in tumor tissues than para-tumor tissues." (PMID 38273348, 2024). "The increased concentration of COL4A1 in TNBC suggests its role in enhancing tumor cell invasion and migration by providing structural support and activating signaling pathways that promote metastasis." (PMID 39850811, 2024). "Myofibroblasts showed high overlap with regions of high COL4A1 expression, and both myofibroblasts and tumor cells showed overlap with the areas of high ITGAV expression." (PMID 39639369, 2024). "Results showed that COL4A1 was negatively correlated with tumor purity, and positively correlated with CD8 + T cell, dendritic cell, macrophage, neutrophil, and CD4 + T-cell infiltration." (PMID 38907304, 2024). "Nonetheless, our study contributes novel insights by revealing a significant increase in COL4A1 expression, along with a strong correlation with tumor-infiltrating immune cells in STAD." (PMID 38907304, 2024). "All examined fibrotic markers α-SMA (Acta2), Col1A1, and Col4A1 and proliferation markers are also dramatically increased in the tumor." (PMID 39796711, 2024). "In this study, analysis conducted on the TCGA database revealed a significant upregulation of COL4A1/2/4 expression in STAD tumor tissues." (PMID 38907304, 2024). "Through a convergence of experimental and database analyses, we consistently observed a marked upregulation of COL4A1 expression in STAD, along with a close association with tumor-infiltrating immune cells." (PMID 38907304, 2024). "MMP2/9 secretion, migration, invasion, and colonization of tumor cells are stimulated by COL4A1 through activation of the PI3K/AKT signaling pathway and DDRs." (PMID 38004422, 2023). "COL4A1 manages the inhibition of cell death; the activation of focal adhesion kinase; the cell cycle; tumor angiogenesis; the PI3K/MAPK, PI3K/AKT, and PRL/PAK1 signaling pathways, and the discoidin domain receptor (DDR) axes." (PMID 38004422, 2023). "COL4A1 is generally located in the basement membrane and is thought to be a barrier to tumor invasion." (PMID 35455650, 2022). "In a genome-wide analysis, TRIM35 was shown as a novel tumor suppressor, and COL4A1 on the 13q34 locus was a frequent amplification target, a finding consistent with our results." (PMID 35814473, 2022). "We also found that COL4A1 mRNA is highly expressed in TECs and that high COL4A1 expression correlates with the level of endothelial infiltration in the tumor mass." (PMID 35455650, 2022). "In this study, we demonstrated that COL4A1 mRNA expression levels are upregulated in various cancer types, and high expression of COL4A1 correlates with poor prognosis in at least four tumor types: LGG, PAAD, SKCM, and STAD." (PMID 35455650, 2022). "The expression levels of COL4A1 were positively correlated with the gene expression levels of these immunosuppressive cytokines in all four analyzed tumor types, LGG (IL10: cor." (PMID 35455650, 2022). "Tumor cell-secreted extracellular matrix molecule such as collagen (COL4A1) can bind to adhesion receptors broadly expressed on many cell types, such as integrin receptor ITGB1." (PMID 36028490, 2022). "Despite some discrepancies in late-stage LGG progression, the association of COL4A1 overexpression with patient overall survival suggests the existence of a common tumor-promoting mechanism related to COL4A1 expression, at least in the four tumors analyzed." (PMID 35455650, 2022).